TNF (tumor necrosis factor)
Diseases named in the same sentence as TNF in open-access papers (continued):
Sharing a sentence is not in itself a finding about the gene and the disease.
psoriasis (continued). "Psoriasis is another chronic inflammatory disease of the skin characterized by an elevated circulating level of IL-1 induced by local overexpression of TNF-α or IL-12/23 p40; the increased circulating level of IL-1 has been shown to be a risk factor for cardiovascular disorders." (PMID 25119884, 2014). "Altered alpha ketoglutaric acid levels may also play a role within the hyperactive immunogenic state of psoriasis, in which lymphocytes, macrophages, and neutrophils secrete the inflammatory cytokines TNF-α, IL-1, and IL-6." (PMID 25580230, 2014). "Several hypotheses regarding psoriasis have been proposed by researchers, who have suggested that activated T lymphocytes, tumor necrosis factor α (TNF-α), IL17/IL23, and so forth play a crucial role in psoriatic inflammatory changes." (PMID 25165479, 2014). "Importantly, the synergistic effects of IL-17 and TNF-alpha are capable of further upregulating IL-6 in psoriasis lesional skin; hence, selective targeting of either IL-17 or TNF-alpha exerts additional beneficial effects by indirectly reducing IL-6 levels." (PMID 25126586, 2014). "For statins, other authors suggest beneficial effects in psoriasis, that might derive from anti-TNF properties of statins." (PMID 25713604, 2014). "Thus, TNF-α stimulation impacts a variety of cells that release mediators required for the pathogenesis of psoriasis." (PMID 25384035, 2014). "Responders were stratified by RA, CD, and psoriasis for each anti-TNF agent." (PMID 24883246, 2014). "Anti-TNF therapy may lead also to paradoxical inflammatory skin (eczema and psoriasis) and joint (polyarthralgia) or ocular (uveitis and scleritis) manifestations." (PMID 25045210, 2014). "Several studies have identified Type 0 biomarkers for pathological skin conditions such as psoriasis and atopic dermatitis, including biomarkers for keratinocyte activity (e.g. presence of K16) and inflammatory response (e.g. up-regulation of IL-8 and TNF-α)." (PMID 25785188, 2014). "Therefore, close attention should be paid to the coexistence of MAG-related neuropathy with psoriasis to avoid side effects of immune therapy, especially anti-TNF-α therapy." (PMID 23286283, 2013). "The mechanisms involved in putative anti-TNFα induced IgA nephritis in psoriasis are uncertain." (PMID 24558628, 2013). "In addition, STAT1-57 genes were repressed in psoriasis lesions following treatment of patients with biologic agents, including anti-TNF therapy (P = 2.1×10−8; GSEA), anti-IL-17A therapy (P = 9.9×10−8; GSEA) and efalizumab (P = 4.5×10−12; GSEA)." (PMID 24260178, 2013). "This raises the possibility that similar than targeting cytokines such as TNF-α, IL-12/23, IL-17, or IL-21 blocking of IL-9 might be of potential benefit in patients with psoriasis and other Th17 cell-mediated autoimmune diseases." (PMID 23335955, 2013). "Anti-TNFα drugs are an established treatment in the management of severe psoriasis." (PMID 24558628, 2013). "The proinflammatory cytokine TNFα plays a key role in the pathogenesis of psoriasis." (PMID 24069534, 2013). "TNF serum levels and in suction skin blister fluids correlate with the severity of psoriasis." (PMID 23531535, 2013). "Currently, there were only 3 case-control studies published to investigate the associations of TNF-α 308 G/A and 238 G/A polymorphisms with psoriasis risk in Asians, and no one studies were published to assess the association in Africans." (PMID 24324571, 2013). "Targeting TNFα in psoriasis patients by therapeutics significantly abates disease symptoms." (PMID 23531535, 2013). "A previous study performed in 99 Caucasian patients (64 with type I psoriasis and 35 with type II psoriasis) showed decreased frequency of the GG genotype and increased frequency of the GA genotype of rs361525 (TNFα gene) in patients with type I psoriasis compared with controls (n = 123)." (PMID 24069534, 2013).
psoriasis (continued). "In particular, NF-κB has emerged as an important TF that can be activated by TNF and other cytokines in psoriasis lesions, potentially providing a mechanism by which KCs integrate inflammatory signals with downstream events allowing for extensive cell division." (PMID 24260178, 2013). "Given the pro-inflammatory cutaneous cytokine milieu which is present in psoriasis, we speculated that cytokines, for example tumour necrosis factor alpha (TNFα) and interferon gamma (IFNγ), may up-regulate intracutaneous PRL production." (PMID 23626671, 2013). "However, R348 does not induce hypercholesterolemia and reduces systemic levels of IL17, IL22, IL23, and TNF, which are important for controlling psoriasis." (PMID 24170986, 2013). "In this report, it was suggested that TNF-α inhibitor therapy may produce aberrant INF-α expression at the tissue level in predisposed individuals and thus promote psoriasis lesion induction similar to infection or injury." (PMID 23573431, 2013). "In addition, VEGF and molecules membership are closely associated with the activity of key inflammatory molecules involved in psoriasis such as TNF and NFKB." (PMID 24396598, 2013). "One recent review reported a role for SNPs in psoriasis-related autoimmune diseases (psoriatic arthritis, rheumatoid arthritis, and Crohn's disease) that could play a role in the response to anti-TNF drugs." (PMID 24069534, 2013). "TNF-α is a cytokine active in psoriasis and PsA that deserves special attention." (PMID 23843781, 2013). "Prolonged TNFα exposure is known to impair T cell responses (namely TCR-induced proliferation and cytokine production) by attenuating T cell receptor signaling, and anti-TNF therapy in patients with psoriasis and inflammatory bowel disease results in improved responses to TCR stimulation ex vivo." (PMID 24236161, 2013). "Moreover systemic as well as intra-articular anti-TNF therapy showed reduction of increased IL-22 level in serum and synovial fluid of psoriasis and PsA patients respectively." (PMID 22417743, 2012). "The inhibition of TNFα has recently gained attention as an important tool in fighting a number of inflammatory processes, as a number of TNFα inhibitors (infliximab, etanercept, and adalimumab) are currently indicated for the treatment of arthritis and psoriasis." (PMID 22745823, 2012). "CD14+ monocytes isolated from both patients with psoriasis and healthy control volunteers were cultured in a cytokine cocktail for 5 days to promote their differentiation into mLCs, then stimulated for 24 h with TNF-α, IL-1β (both 100 ng/mL) or medium alone." (PMID 21933242, 2012). "The molecular scar represents a group of genes that are still expressed at the end of 12 weeks of successful treatment with etanercept, an anti-TNF agent used for psoriasis, at the time point where there was complete clinical resolution and no visible skin inflammation." (PMID 22957057, 2012). "Recently, it was reported that the development of ANAs and anti-ds-DNA Abs with anti-TNF therapies may act as a marker of forthcoming treatment failure in patients with psoriasis." (PMID 22192852, 2011). "If IL-12 and IL-23 are less potent immune mediators than TNFα is, then TNFα knockdown may have a more profound therapeutic effect on psoriasis." (PMID 21352568, 2011). "However, in contrast to local anti-TNFα treatment, the therapeutic potential of targeting IL-12B at the RNA level in psoriasis is questioned." (PMID 21352568, 2011). "Both TNF and iNOS are well established pro-inflammatory mediators in psoriasis." (PMID 21295490, 2011). "Collectively these data suggest that the clinical benefit of TNF neutralization in psoriasis might derive from the attenuation of inflammatory DC activity in the lesions." (PMID 21295490, 2011). "Similarly, TNF-alpha is a key mediator in psoriasis and interestingly TNF-alpha levels are elevated in “congestive heart failure” as well." (PMID 21063523, 2010).
psoriasis (continued). "Additionally, in other immune-mediated inflammatory diseases, such as psoriasis, where anti TNF-a agents constitute a within label treatment, different antiTNF-α agents display variable efficacy in different patients." (PMID 20300578, 2010). "Similarly, the pathogenesis of psoriasis involves key Th1 and Th17 inducing cytokines like TNFα, IL-1β, IL-2, IL-6, IL-10, IL-12p70, IL-23, CCL2, 3, 4, 5, 20, CXCL1, 8, 9 and 10, many of which are induced by cocktail treated DCs." (PMID 20663192, 2010). "The effectiveness of the anti-TNF treatment of psoriasis validated the first axis." (PMID 20606888, 2010). "Furthermore, disease resolution in psoriasis patients following TNF blockade correlates with reduced Th17 responses." (PMID 19627579, 2009). "Interestingly, a recent study has reported an increased IFNα expression and more severe psoriatic skin lesions in patients treated with TNF blockers, implicating IFNα in the pathogenesis of psoriasis." (PMID 19563672, 2009). "Certain drugs like anti-TNF have positive effects in RA, psoriasis and ankylosing spondylitis as compared to MS suggesting that certain molecules may have diametric roles in different diseases." (PMID 20041220, 2009). "On the basis of experience gained in cytokine modulation therapy of chronic inflammatory diseases such as RA and psoriasis, the application of TNF- inhibitors represents a novel, more specific, and effective therapeutic option for distinct chronic inflammatory diseases." (PMID 20101303, 2009). "In the epidermal milieu of psoriasis, activated CD4+ helper T-cells interact with CD8+ suppressor T-cells, dendritic cells, and keratinocytes, resulting in production of TH1-associated cytokines, the most important of which is tumor necrosis factor (TNF)." (PMID 18366773, 2008). "Our findings show the existence of a direct relationship between MMP-9 and TNF-α production strongly suggesting that MMP-9 may play a key role in the skin inflammatory process in psoriasis." (PMID 17022813, 2006). "However, for psoriasis, while TNF-α inhibitors can be used in treatment, they may also induce new-onset psoriasis or exacerbate existing stable psoriasis." (PMID 41496107, 2026). "The middle panel contrasts normal versus psoriatic epidermis, emphasizing the pathological hallmarks of psoriasis, including epidermal hyperplasia, elongated rete ridges, leukocyte infiltration, and excessive NF-κB activity in KCs, driving pro-inflammatory cytokine release (e.g., TNF-α/IL-17)." (PMID 41226338, 2025). "In particular, the occasional presence of eosinophils and plasma cells has been reported in paradoxical psoriasiform plaques induced by anti-TNF-α therapy—a potential clue to distinguish them from classic psoriasis, which may also be useful in the diagnosis of PsoDermatitis." (PMID 41517378, 2025). "Blautia, which upregulates intestinal regulatory T cells and promotes biotransformation, and Ruminococcus, which promotes immune activation and the production of cytokines like TNF-α, suggest that immune dysregulation driven by abnormal gut microbiota may play a key role in psoriasis pathogenesis." (PMID 41425939, 2025). "Furthermore, subcutaneous administration of the fused EVs in a psoriasis-like mouse model elevated expression of the M2 macrophage marker Arg1 and significantly reduced levels of inflammatory cytokines, including IL-1β, IL-6, and TNF-α, in affected skin." (PMID 41226338, 2025). "Moreover, MOG drives Th17/Th1 cells to produce IL-17A and TNF-α, which may have a potential impact on psoriasis." (PMID 40564099, 2025). "The exploration of therapeutic interventions, including TNF-α inhibitors and biological therapies that target selectins, reveals encouraging possibilities for enhancing endothelial function, reducing inflammation, and achieving better health outcomes in patients with psoriasis." (PMID 39859506, 2025).
psoriasis (continued). "Furthermore, the pathophysiology of uterine leiomyomatosis and psoriasis could be associated through common pathways such as WNT/β-catenin, TNF-α, VEGF, and bFGF." (PMID 39910492, 2025). "This study seeks to determine whether biologic therapies influence the development and prevalence of SKs in psoriasis patients and whether different biologic agents (TNF-α inhibitors, IL-17 inhibitors, and IL-23 inhibitors) have distinct effects on SK occurrence." (PMID 40141829, 2025). "Psoriasis is mediated by T lymphocytes, in particular Th1 and Th17, and dendritic cells that are activated and elevated in skin lesions and migrate and release proinflammatory cytokines such as IL-1 and IL-6, but also TNF-a, which favor keratinocyte proliferation and inflammation." (PMID 40003621, 2025). "The main study hypothesis regards the potential significant additional effect of periodontal therapy to TNF‐α inhibitor in reducing the severity and extent of psoriasis via the reduction of systemic inflammation in a combined experimental model of periodontitis and psoriasis." (PMID 40277096, 2025). "Consequently, resistin has a strong link with TNF-α, a major inflammatory mediator in psoriasis." (PMID 40724556, 2025). "Indeed, psoriasis patients exposed to TNF blockers in one series had a significantly higher odds of developing myopathy (OR ~4.45), suggesting TNF may also have complex immunoregulatory roles." (PMID 40861474, 2025). "ERN has been shown to diminish TNF-α-induced inflammation and keratinocyte hyperproliferation in both in vitro and in vivo models, indicating it could serve as a reliable and efficient treatment for psoriasis." (PMID 40667480, 2025). "Furthermore, integrating gene expression data with therapeutic response profiles (e.g., to IL-17 or TNF inhibitors) could facilitate the identification of novel predictive biomarkers and advance personalized treatment strategies in psoriasis." (PMID 41328434, 2025). "This unexpected finding may reflect disease-specific immune dysregulation or differences in treatment regimens, as RA patients in our study were less likely to have received anti-TNF-α agents compared to those with psoriasis (59.5% overall, with adalimumab predominant)." (PMID 40725683, 2025). "Psoriasis is a chronic, immune-mediated inflammatory skin disease characterized by hyperproliferation and abnormal differentiation of keratinocytes, driven by dysregulated interactions between T cells, dendritic cells, and cytokines, such as TNF-α, IL-17, and IL-23." (PMID 41393637, 2025). "Similarly, a recent retrospective cohort study demonstrated that treatment with TNF‐α inhibitors, as well as IL‐12/23, IL‐17, and IL‐23 inhibitors, is associated with a reduced risk of both new‐onset and recurrent MACE in patients with psoriasis." (PMID 40916619, 2025). "A recent retrospective cohort study demonstrated that both TNF‐α inhibitors and non‐TNF‐α biologics (interleukin [IL]‐12/23, IL‐17, and IL‐23 inhibitors) are associated with a reduced risk of new‐onset and recurrent major adverse cardiovascular events (MACE) in patients with psoriasis." (PMID 40916619, 2025). "Conversely, TNF-α, a key inflammatory factor in psoriasis, may downregulate SIRT1 expression." (PMID 41002407, 2025). "Thus, TNF-α was used to induce psoriasis-like hyperkeratosis in HaCaT cells." (PMID 40507893, 2025). "Moreover, in this combined model of periodontitis and psoriasis, circulating levels of inflammatory markers further decreased when both periodontal therapy and TNF‐α inhibitor were administered, thus suggesting a potential association linking the two diseases in humans." (PMID 40277096, 2025). "These factors include the interleukins, such as IL‐1, IL‐6, and IL‐8, monocyte chemoattractant protein (MCP)‐1, TNF‐α, and granulocyte‐macrophage colony‐stimulating factor (GM‐CSF), which collectively play crucial roles in various inflammatory problems such as atopic dermatitis and psoriasis." (PMID 39968713, 2025).
psoriasis (continued). "Therefore, TAC and TNF-α siRNA together can exert an amplifying effect on psoriasis." (PMID 40299379, 2025). "Importantly, an antiferroptotic agent, liproxstatin-1, was as effective as clinically relevant biological IL-12/IL-23/TNF-α–targeting therapies or the depletion of T cells in completely abrogating molecular, biochemical, and morphological features of psoriasis." (PMID 39570671, 2024). "Finally, the analysis of selected innate immunity molecules showed that the type I IFN-β and the lymphotoxins LT-α and LT-β (belonging to the TNF cytokine family) mRNA are poorly expressed in psoriasis lesions induced by anti-PD-1, as compared to anti-TNF-α-induced psoriasis." (PMID 38495872, 2024). "When environmental and genetic factors activate plasmacytoid dendritic cells, cytokines such as TNF-α, IL-6, and IL-1β are released, leading to T cell-mediated inflammation, keratinocyte activation, and excessive proliferation, resulting in inflamed skin patches characteristic of psoriasis." (PMID 39170985, 2024). "Twelve biologics targeting cytokines TNF-α (tumor necrosis factor alpha), IL-12/23 (interleukin 12/23), IL-17 (interleukin 17), and IL-23 (interleukin 23) have been approved for the treatment of moderate to severe psoriasis in the United States, including most recently bimekizumab in October 2023." (PMID 39083767, 2024). "In a previous Korean nationwide nested case-control analysis that was conducted to assess the risk of cancer, TB, and serious infections in patients with AS, PsA, and psoriasis treated with IL-17 and TNF-α inhibitors, it was shown that IL-17 inhibitors may offer an advantage in terms of TB risk." (PMID 38674225, 2024). "The presence of TNF-α in cardiac tissues of psoriatic patients could potentially be related to the inflammatory activity of EAT, providing a new perspective on the potential link between EAT, systemic inflammation, and cardiovascular risk in psoriasis." (PMID 39200903, 2024). "Therefore, a decrease in this genus may lead to changes in the immune response to the gut microbiota, promoting the upregulation of inflammatory factors IL-17 and TNF-α, further exacerbating the adverse effects related to the pathogenesis of psoriasis." (PMID 39170985, 2024). "In rare cases, TNF inhibitors may also paradoxically induce psoriasis." (PMID 38347543, 2024). "TNF-α facilitates IL-23 release by DCs, promotes T-cell infiltration through interaction with keratinocytes, and collaborates with IL-17 to stimulate inflammatory cytokine and chemokine production in keratinocytes, which amplifies the psoriasis inflammatory cascade." (PMID 38892253, 2024). "The absence of the tumor necrosis factor (TNFAIP3) gene was linked to inflammation in psoriasis." (PMID 39766858, 2024). "Notably, TNF-α is highly expressed in both Psoriasis and MS." (PMID 39125666, 2024). "Furthermore, TNF inhibition may paradoxically increase the differentiation of Th1/Th17 cells and cause a dysregulated IFN response due to the regulatory nature of TNF, leading to autoantibody production and psoriasis after anti-TNF therapy." (PMID 39062908, 2024). "In this regard, it might be interesting to extend our study on the role of POE in the immune-mediated pathogenesis of psoriasis not only by inhibiting upstream signaling agents, such as TNF expression, but also by inhibiting downstream signaling agents of the canonical NF-κB pathway." (PMID 39057409, 2024). "Our findings align with the known functions of IL-6, IL-17, and TNF-α inhibitors, indicating that XYAS, LXJD, and QXAS could significantly reduce IL-6, IL-17, and TNF-α levels and exert an inhibitory effect on epidermal thickening in mice with psoriasis and SDs." (PMID 39411067, 2024).